TERT (telomerase reverse transcriptase)
Diseases named in the same sentence as TERT in open-access papers (continued):
Sharing a sentence is not in itself a finding about the gene and the disease.
glioma (continued). "Reports on mutations within the core promoter of the telomerase reverse transcriptase (TERT) gene in different cancers have consistently shown occurrence at highest frequencies in adult gliomas." (PMID 25797251, 2015). "The NHGRI GWAS catalog (accessed on 17th September 2014) identified 21 published GWAS linking TERT to breast cancer, bladder cancer, testicular cancer, lung cancer, glioma and prostate cancer and 11 GWAS linking FGFR2 to breast cancer." (PMID 26431041, 2015). "A combination of TERT promoter and IDH mutations support placement of gliomas into the subgroups, which is also reflected in survival and can be of considerable use in making appropriate treatment decisions." (PMID 25797251, 2015). "Frequent mutations in the promoter region of telomerase reverse transcriptase (TERT) are detected in various types of tumors, including gliomas." (PMID 26314843, 2015). "We recently showed that glioma risk alleles near TERC and TERT are associated with increased leukocyte telomere length (LTL)." (PMID 26646793, 2015). "Genotoxic therapies were independent prognostic factors in IDH mutated grade II and grade III gliomas but lost significance in IDH mutated subgroups divided by the status of 1p/19q codeletion and TERT promoter mutations." (PMID 26314843, 2015). "This suggests that additional LTL-associated SNPs outside the TERC, TERT and RTEL1 regions also confer glioma risk." (PMID 26646793, 2015). "To define the co-occurrence of IDH1/2 mutations and the presence of TERT promoter mutations, we determined the status of IDH1 and IDH2 mutations in the same cohort of 473 gliomas and identified mutations in 47.9% (227/473) of tumors." (PMID 24722048, 2014). "The effect of TERT promoter mutations on the transcriptional activity of the TERT gene under hypoxic and TMZ treatment conditions was investigated in glioma cells using the luciferase assay." (PMID 24937153, 2014). "Future studies will focus on elucidating the mechanisms by which TERT promoter mutations confer resistance to TMZ treatment, and on examining the association between these mutations and others that promote glioma progression." (PMID 24937153, 2014). "Recent findings have established frequent mutations in the promoter region of telomerase reverse transcriptase (TERT) in a multitude of cancers, including melanomas, liposarcomas, bladder cancer, urinary tract cancers, and gliomas." (PMID 24722048, 2014). "Frequent mutations in isocitrate dehydrogenase 1 and 2 (IDH1 and IDH2) and the promoter of telomerase reverse transcriptase (TERT) represent two significant discoveries in glioma genomics." (PMID 24722048, 2014). "TERT mRNA expression levels and telomerase activity in the C6 glioma cell line was used as a positive control." (PMID 24887495, 2014). "The telomerase reverse transcriptase TERT promotes stem-like features and drug resistance in both glioma and breast cancer, and correlates with tumorigenic capacity of melanoma cells." (PMID 24098529, 2013). "Overexpression of TERT and telomerase activity has been observed in many tumors, such as lung cancer, skin cancer, glioma." (PMID 23738012, 2013). "Five of the genes, TERT, SLC6A18, CLPTM1L, and CDKN2A/B, have previously been shown to be associated with glioma by other GWA studies." (PMID 21827660, 2011). "In the remaining cases, information on CDKN2A/B status was missing in 40 patients with IDH-mutant astrocytoma, and information on molecular features of glioblastoma (TERT mutation, EGFR amplification, 7p + /10q-) was missing in 27 patients with IDH-wildtype glioma." (PMID 39954095, 2025). "Giannini also believed that IDH wild-type grade II glioma combined with a TERT mutation in isolation was not suitable to be defined as glioblastoma, IDH wild-type." (PMID 41035663, 2025).
glioma (continued). "Specifically, gliomas with higher TBR values tend to have higher Ki67 and TERT promoter mutation rates, indicating increased tumor proliferative activity, this may be related to a higher number of active tumor cells, leading to increased FET uptake." (PMID 40149633, 2025). "Additionally, neocortical gliomas (including GBM, WHO grade 3 glioma) had significantly higher TERT promoter mutation rates and Ki67." (PMID 40149633, 2025). "TERT Promoter Mutations: Abnormal reactivation of Telomerase Reverse Transcriptase (TERT) is common in solid tumors, particularly those arising from tissues with low self-renewal capacity, such as melanoma, thyroid cancer, and CNS tumors, including gliomas." (PMID 40426960, 2025). "TERT promoter mutations or EGFR amplification have not yet been described in the setting of NF1-associated gliomas, while alteration as a gain of chromosome 7 and loss of 10 were rarely observed." (PMID 40277798, 2025). "Finally, TERT resulted hypomethylated and therefore actively expressed in high-grade gliomas, which is consistent with TERT overexpression in more aggressive tumors." (PMID 41153666, 2025). "Oligodendroglioma (Omut-IDH,codel-1p/19q,G3), in which TERT (3/4 Patients), CIC (3/4 Patients), FUBP1 (1/4 Patients), and NOTCH1 promoter (1/4 Patients), which corroborates the frequency of mutations in these genes in patients with high-grade gliomas." (PMID 39767683, 2024). "Gliomas that do not carry TERT promoter mutations frequently harbor mutations of the telomere binding protein, activating the pathway of alternative lengthening of telomeres (ALT)." (PMID 38532312, 2024). "To compare the subclonal diversity of primary cultures with differentiated glioma cells cultured in serum, we included the U87MG cell line derived from an IDH wildtype high-grade glioma with typical GBM mutations in the NF1, PTEN and TERT genes." (PMID 38414005, 2024). "Preoperative multi‐modal magnetic resonance imaging radiomic study could distinguish IDH‐mutant TERT promoter‐mutant gliomas from other gliomas." (PMID 36176070, 2023). "Additionally, Altera is designed to profile 440 medically important genes by whole genome sequencing (WGS) including all glioma-relevant SNPs except for p-TERT DNA sequence alterations." (PMID 37908227, 2023). "Of note, the number of neutrophils was not increased in the peripheral blood of patients with TERT-mutated gliomas, suggesting that tumor infiltration by neutrophils is due to cytokine chemotaxis." (PMID 38275375, 2023). "Personalis (Menlo Park, United States) offers a panel with 267 genes for solid tumor molecular profiling including most of the glioma-associated genes, but missing oligodendroglioma markers, namely, FUBBP1, 1p/19q-codeletion, and p-TERT (Personalis | NeXT Dx, 2023)." (PMID 37908227, 2023). "Moreover, most APS gliomas are low-grade gliomas with a high ratio of IDH and TERT mutations and MGMT methylation." (PMID 38111070, 2023). "The heatmap showed the relationship between high‐ and low‐risk groups and clinical features of glioma patients, such as gender, age, WHO grade, IDH mutation status, KPS, 1p/19q codeletion, TERT promoter status, and MGMT promoter methylation status, in TCGA database." (PMID 36560848, 2023).
glioma (continued). "The molecular characterization of fusion-positive glioma revealed that FGFR3::TACC3 is mutually exclusive with IDH and H3 mutation but it is often associated with TERT promoter mutation and + 7/−10 chromosome copy-number changes and amplification of CDK4 and /or MDM2." (PMID 36647073, 2023). "In addition, TERT promoter mutation occurs almost simultaneously with IDH mutations and 1p/19q co-deletion in gliomas." (PMID 37570630, 2023). "Moreover, the presence of a TERT promoter mutation was evaluated, with the usually mutually exclusive presence of TERT promoter mutations and ATRX mutations described in gliomas as well as cutaneous melanomas." (PMID 37629169, 2023). "Gliomas with both IDH and TERT promoter mutations have been shown to derive a better prognosis." (PMID 36176070, 2023). "Gliomas with the p-TERT mutation have shorter telomere lengths compared to gliomas without them, but at the same time expression of TERT is elevated." (PMID 37908227, 2023). "In this study, IDH1 gene mutation was detected in 86 cases (74.8%), IDH2 gene mutation in five cases (4.4%) and TERT promoter mutation in 68 cases (59.1%), the results showed that IDH1/2 and TERT genes were related factors affecting the prognosis of patients with glioma." (PMID 37250582, 2023). "Survival in gliomas with a TERT mutation and 1p19q co-deletion (median survival 58.2 months) was higher than in those without TERT mutation and 1p19q codeletion (median survival 42 months)." (PMID 34558656, 2022). "In general, TERT promoter mutations confer survival benefits in patients with IDH-mutant gliomas, while they are negative prognosticators in those with IDH-wildtype tumors." (PMID 36614997, 2022). "IDH and TERT genotype were mutant in 45 (40.54%) and 55 (49.55%) of the 111 gliomas." (PMID 36471242, 2022). "TERTp mutations activate TERT to maintain telomeres in cancer cells, but generally at a shorter length relative to other telomere maintenance mechanisms, such as alternative lengthening of telomeres in ATRX mutant glioma." (PMID 36130485, 2022). "To determine whether the TERT status provides additional prognostic information, we analyzed the relationship between overall survival in glioma patients classified according to the WHO 2016 criteria in our cohort." (PMID 34558656, 2022). "Notably, patients with TERT promoter mutant high-grade infiltrating gliomas of the spinal cord had significantly lower overall survival compared to those with TERT wild-type tumors—a group that includes all H3K27M-mutant cases." (PMID 35267601, 2022). "further fine-graded lower-grade gliomas with the addition of TERT status." (PMID 35558510, 2022). "Furthermore, we correlated PD-L1 expression with molecular glioma hallmarks such as MGMT-promoter methylation, IDH1/2 mutations, TERT promoter mutations and LOH1p/19q." (PMID 33963441, 2021). "Suggestive associations (1.58 × 10−4 < P < 0.05) were observed between leukocyte telomere length (LTL) with all glioma (ORSD = 3.91, P = 9.24 × 10−3) and GBM (ORSD = 4.86, P = 3.23 × 10−2), but the association was primarily driven by the TERT variant rs2736100." (PMID 33020596, 2021). "How the molecular mechanistic details of TERT be able to modulate stemness of glioma remains unclear." (PMID 33869033, 2021). "IDH-mutant glioma with ATRX and TERT mutations was always associated with favorable survival." (PMID 34220791, 2021).
glioma (continued). "TERT mutation status, IDH mutation, and 1p-19q codeletion status data were obtained from 614 glioma cases from the Cancer Genome Atlas, and 325 cases from the Chinese Glioma Genome Atlas." (PMID 33996815, 2021). "In addition, recently, the WHO grading system of central nervous system tumors was updated to require genetic testing including IDH mutation, TERT promoter mutation, H3K27M mutation, 1p/19q codeletion for the precise diagnosis of gliomas." (PMID 34298824, 2021). "Four of the IEAA-associated SNPs (rs2736100 in TERT, rs2275558 in PBX1, rs144317085 in TET2, and rs2492286 in RPN1) were associated with 16 unique traits including multiple cancers (e.g., lung cancer, glioma) and blood cell counts (e.g., platelet count, eosinophil count, red blood cell count)." (PMID 34187551, 2021). "Knockdown of human TERT inhibited cell proliferation and migration of gliomas in vivo." (PMID 34159191, 2021). "Here we show that TERT and ALT are associated with unique 1H-magnetic resonance spectroscopy (MRS)-detectable metabolic signatures in genetically-engineered and patient-derived glioma models and patient biopsies." (PMID 33397920, 2021). "Additionally, DDX60 favored its expression in mesenchymal and classical subtype, MGMT unmethylated (P < 0.001), ATRX wild-type (P < 0.001), TERT promoter mutated (P < 0.001), and IDH wild-type gliomas (P < 0.001)." (PMID 34178649, 2021). "We substantiated the idea of TERT and LEP being the risk factors, and LEP and PON1 as protective factors, affecting the immune cell infiltration level and the levels of proinflammatory factors in glioma." (PMID 34114970, 2021). "Moreover, we observed that DDX60 was significantly overexpressed in glioma with IDH wild-type, ATRX wild-type, MGMT unmethylated as well as TERT promoter mutated." (PMID 34178649, 2021). "Our preliminary bioinformatics from TCGA and CGGA mining unerringly exhibit that GRPEL2 gene expression correlates with WHO tumor grades (p < 0.001), IDH mutation status (p < 0.001), and overall survival (p < 0.001), and highly correlated with TERT expression in gliomas." (PMID 34884508, 2021). "Conclusively, our study demonstrates that three radiomic models based on pre-operative MR data for noninvasive, individualized prediction of IDH mutation, 1p/19q codeletion, and TERT promoter mutation in gliomas patients regardless of grades." (PMID 34312469, 2021). "BRAF mutations and TERT promoter mutations have synergies in the diagnosis of thyroid cancer, and we have also found synergies between BRAF mutations and TERT promoter mutations in patients with melanomas, epithelial glioblastomas and gliomas." (PMID 34923978, 2021). "In forty-six glioma patients, the number of IDH mutated patients were 21 (45.7%), IDH wild-type were 25 (54.3%), TERT mutated were 29(63%), TERT wild-type were 17(37%), MGMT promotor methylation were 33(71.7%), MGMT promotor un-methylation were 13(28.3%) respectively." (PMID 34814870, 2021). "However, there are few studies on the relationship between the status of IDH, MGMT, TERT and perfusion indicators in glioma patients." (PMID 34814870, 2021). "We further tested the hypothesis with well-known molecular markers in glioma, including IDH mutation, 1p/19q codeletion, TERT promoter mutations, and MGMT promoter methylation." (PMID 33981597, 2021). "Our results showed that TERT promoter mutations predict favorable prognosis regardless of 1p/19q status in IDH-mutated gliomas." (PMID 33228806, 2020).
glioma (continued). "Another mechanism of interest in TERT promoter mutant gliomas is occurrence of BFB cycles, which create chromosomal instability until the acquisition of telomerase activity, however the current study was limited due to lack of a reliable bioinformatics tool for its detection from WES data." (PMID 33297360, 2020). "For example, those infiltrating gliomas with FGFR-TACC fusions may present with other oncogenic alterations including CDKN2A loss, CDK4 amplification, MDM2 amplification and/or TERT promoter mutations." (PMID 32493417, 2020). "From our results, the OS of gliomas can be further stratified into four distinct survival subgroups with ascending survival time as follow: TERT-mut/MGMT-unmeth << TERT-wt/MGMT-unmeth << TERT-wt/MGMT-meth << TERT-mut/MGMT-meth which is consistent with previous reports." (PMID 32957941, 2020). "In glioma, the TERT promotor mutant is related with the recruitment of the multimeric GABP transcription factor, which might regulate a mass of proto-oncogene expression." (PMID 33195221, 2020). "Our results showed that TERT promoter mutations in IDH-mutated gliomas predict favorable prognosis regardless of 1p/19q status, highlighting the significant role of TERT promoter mutations as a prognostic marker." (PMID 33228806, 2020). "We and others have shown that TERT promoter mutations are frequently observed (> 90%) in oligodendrogliomas with mutant IDH and 1p/19q codeletion, and that the presence of TERT promoter mutations is associated with favorable outcomes in IDH-mutated gliomas." (PMID 33228806, 2020). "Our results provide strong evidence that TERT promoter mutation confers a favorable prognosis regardless of the 1p/19q status in IDH-mutated gliomas." (PMID 33228806, 2020). "As to the prognostic significance of TERT, differences results depend on subtype of the gliomas." (PMID 32047544, 2020). "Our results demonstrate that TERT promoter mutation predicts favorable prognosis independent of 1p/19q codeletion in IDH-mutated gliomas." (PMID 33228806, 2020). "Moreover, low level of ZDHHC23 was also associated with 1p/19q co-deletion (p < 0.01), loss of TERT (p < 0.05), and mutated ATRX (p < 0.01) in the glioma tumors." (PMID 30658672, 2019). "Of note, TERT mutations have a prognostic role in gliomas, being a negative prognostic factor in primary GBM without MGMT methylation." (PMID 30984267, 2019). "Moreover, TERT re-expression partly rescued double-mutant glioma cells from the YK-4-279-induced growth inhibitory effect." (PMID 31391125, 2019). "Identification of IDH1/2 (IDH) mutation and/or TERT promoter (pTERT) mutation is crucial for reaching a correct diagnosis and choosing the most appropriate treatment for patients harboring WHO grade II/III gliomas." (PMID 31889117, 2019). "Moreover, recent publications demonstrate that acquired somatic mutations in TERT and α-thalassemia/mental retardation syndrome X-linked protein (ATRX) can affect telomere maintenance in tumor cells and are important in glioma development and prognosis." (PMID 30625996, 2019). "The TWAS reported an association between genetically predicted TERT gene expression levels and risk of both GBM and non-GBM, which is in line with our finding that the TERT gene variant is associated with risk of glioma, regardless of IDH mutation status." (PMID 31842352, 2019). "Therefore, this study verified that TERT promoter mutations would be an important biomarker in grade II and III gliomas." (PMID 31623593, 2019). "TERT promoter mutations are thought to characterize primary as opposed to secondary GBM (i.e., GBM developing from a preexistent lower-grade glioma), and may play a role as a prognostic factor." (PMID 31083587, 2019).